MIR6820 (microRNA 6820)
Synonyms: hsa-mir-6820
Gene: MicroRNA gene on chromosome 22 (37,967,563 to 37,967,624, forward strand). Ensembl gene ENSG00000284289.
Homologues: Orthologues: chimpanzee MIR6820 (100% identical).